CCR7 (C-C motif chemokine receptor 7)
Diseases named in the same sentence as CCR7 in open-access papers (continued):
Sharing a sentence is not in itself a finding about the gene and the disease.
breast cancer (continued). "Next, the inhibitory effect of let-7a was determined by using synthetic anti-let-7a oligo-nucleotides in MCF-7 breast cancer cells, which express a high level of let-7a and a low level of CCR7, with a high level of CCL21 expression." (PMID 22251626, 2012). "The expression of let-7a and CCR7 was examined in 15 breast cancer patients by quantitative RT-PCR analysis and Western blotting, respectively." (PMID 22251626, 2012). "CCR7 has been reported to be expressed on cancer cells from various origins, including breast cancer cells, and its expression correlates with lymph node involvement and to some extent with prognosis." (PMID 21624121, 2011). "Chemokines CCL19, CCL20 and CCL21 and their receptors CCR6 and CCR7, were assessed as potential biomarkers of metastatic dissemination in primary breast cancer." (PMID 21624121, 2011). "In previously reported series, CCR7 expression had been described on tumor cells from breast cancer as well as from other tumors such as gastric and lung cancer but not on cells in the tumor stroma." (PMID 21624121, 2011). "They proposed that the ideal CCL21 concentration for CCR7 expression in breast carcinoma is 50-500 nmol/L." (PMID 21548969, 2011). "In this study, the expression of both CXCR4 and CCR7 is combined to evaluate their contribution in the lymph node metastasis of breast cancer." (PMID 20181250, 2010). "Unlike CXCL12, however, CC chemokine ligand-21 (CCL21) - the ligand for CC chemokine receptor-7 (CCR7) - is highly expressed in the lymph nodes of breast cancer patients." (PMID 20181250, 2010). "Results of this study revealed that 70% of primary breast cancer tissues and 77% of metastasis cancer cells in lymph nodes expressed CCR7." (PMID 20181250, 2010). "We used HLA-A*0201+ monocyte-derived DCs loaded with killed allogeneic breast cancer cells to prime in vitro autologous naïve CD45RA+CCR7+CD45RO-CD8+ T cells." (PMID 17129372, 2006). "Furthermore, the activation of the CCR7/CCL21 axis by TGF-β1-induced EMT enhances the migration of breast cancer cells via the lymphatic system." (PMID 40333202, 2025). "Another well-studied chemokine receptor involved in breast cancer metastasis is CCR7." (PMID 39982274, 2025). "High CCR7 expression has been found to be linked to poor overall survival in breast cancer patients, independent of other clinicopathological variables." (PMID 40299690, 2025). "Specifically, the CCL19/CCR7 signaling pathway assumes a multifunctional role in breast cancer." (PMID 37944262, 2023). "Finally, we found that CCR7 was associated with cell migration and angiogenesis by knocking down CCR7 expression in breast cancer cells." (PMID 37864213, 2023). "The realm of breast cancer has been a focal point in the exploration of the CCL19/CCR7 pathway." (PMID 37944262, 2023). "Furthermore, CCR7 is correlated with lymphatic metastasis and poor prognosis in different types of breast cancer, while let-7a has been found to suppress breast cancer cell migration and invasion through the downregulation of CCR7 expression." (PMID 36243683, 2022). "Additionally, in luminal B breast cancers, CCR7 expression correlates with Notch to promote tumor growth or stemness." (PMID 35203305, 2022). "In addition, CCR7 can be downregulated by topotecan, a semi-synthetic analogue of camptothecin, thereby inhibiting metastasis in breast cancer." (PMID 35280672, 2022). "CCR7 expression can alter the metastatic destination of breast cancer cells." (PMID 35203305, 2022). "In breast cancer, TGF-β1 activates a Smad protein-linked pathway, resulting in EMT phenotype and lymphatic migration in response to CCL21 release from lymphatic endothelial cells and chemotaxis of CCR7-expressing breast cancer cells." (PMID 35203305, 2022). "Although not well studied, there is evidence that splice variants of CCR7 can significantly positively or negatively affect the progression of breast cancer and patient survival, at least for the basal-like breast cancer subtype." (PMID 35203305, 2022).
breast cancer (continued). "Low-grade luminal A tumors expressed lower levels of CCR7 than more metastatic breast cancers." (PMID 35203305, 2022). "Ets-1 was also shown to bind to the CCR7 promoter and there was a good correlation between Ets-1 expression and CCR7 expression in basal-type breast cancer cell lines, such as MDA-MD-231, suggesting that Ets-1 is a likely mediator of CCR7 effects including cancer cell migration." (PMID 35203305, 2022). "Conversely, CCR7 inhibition reversed the breast cancer cell migratory and EMT functions." (PMID 35203305, 2022). "In addition, CCR7 mRNA levels were elevated in 12 primary human invasive lobular or ductal breast carcinomas when compared to normal mammary gland tissues." (PMID 35203305, 2022). "Other studies have highlighted the key contribution of let-7a in breast cancer cell and cholesteatoma keratinocytes: let-7a suppressed migration and invasion of breast cancer cell by downregulating CCR7 expression, while it acts as a suppressor of growth and invasion of cholesteatoma keratinocytes." (PMID 33750398, 2021). "Considering the significance previously assigned to the GPCR association for their specific activity, we hypothesised that CXCR4 and CCR7 may heterodimerize to exert their pro-invasive function in mammary tumours." (PMID 34685420, 2021). "Therefore, CCL21 is known to improve immunogenicity in breast cancer in tandem with its receptor CCR7." (PMID 34160019, 2021). "CXCR4 and CCR7 surface expression, measured by flow cytometry, was similar between the breast cancer cell lines, indicating that observed differences in ligand cooperativity in metastatic vs non-metastatic cells is not due to the differences in levels of receptor expression." (PMID 34685420, 2021). "Interestingly, CCR7 signaling has also been reported to be involved in the amplification of a pool of cancer stem-like cells in breast cancer." (PMID 34685565, 2021). "Furthermore, TGF-β-induced EMT has been identified as a trigger of CCR7 expression in breast cancer cells." (PMID 34685565, 2021). "We found the specific expression and prognostic value of CCR7 in breast cancer." (PMID 34507558, 2021). "We detected a significant increase in the specific FRET signal over the control in invasive breast cancer cell lines only, suggesting that the CXCR4 and CCR7 association may be linked to the invasive breast cancer phenotype." (PMID 34685420, 2021). "The complete picture of the role and involvement of the CCL21/CCR7 pair in breast cancer is still undergoing development, but there are at least two areas in which this axis has been shown to be actively involved, including lymph nodes metastasis and immune response modulation." (PMID 34298676, 2021). "Despite all the evidence linking CCR7 expression to a poorer prognosis, still much remains unknown about the exact mechanisms behind its upregulation and its role in breast cancer progression, which will be discussed in details in this review." (PMID 32340161, 2020). "On the basis of this review, CCR7 has a critical role in breast cancer progression." (PMID 32340161, 2020). "The CCR7 expression was evaluated in breast cancer cells in vitro to ascertain whether the rates of expression of a chemokine receptor contribute to the pathogenicity of breast cancer." (PMID 32340161, 2020). "Thus, in this review, we summarize the essential roles of CCR7 and its receptors in breast cancer progression." (PMID 32340161, 2020). "Therefore, the interactions between this essential post-transcriptional regulation and patient survival should be carefully investigated in correlation with CCR7 alternative splicing in breast cancer." (PMID 32340161, 2020). "Clinical studies revealed that breast cancer tumors show cytoplasmic CCR7 expression." (PMID 32340161, 2020). "CCR7 has also been linked to the creation of new blood and lymphatic vessels in breast cancer patient samples, though the mechanism is still not well understood." (PMID 32340161, 2020).
breast cancer (continued). "Therefore, further studies are essential to illustrate the distinct roles of CCR7 in cancer progression and validate its potential as a preventive bio-factor for human breast cancer metastasis by targeting chemokine receptor genes." (PMID 32340161, 2020). "Lymphatic endothelial cells have been reported to highly express CCL21, whereas its receptor CCR7 is highly expressed in breast cancer cells and melanoma cells and predicted to be the mechanism by which breast cancer and melanoma preferentially metastasize to lymph nodes." (PMID 30705401, 2019). "Moreover, reduction of CCR7 expression in breast cancer inhibited metastasis and single-chain antibodies blocking CCR7 (MSM R707) were found able to inhibit brain metastasis of T-cell acute lymphoblastic leukemia." (PMID 30894861, 2019). "Activation of CCL21/CCR7 axis could induce tumor progression and metastasis in melanoma, breast cancer and colorectal cancer." (PMID 31523177, 2019). "Although Notch proteins are known to regulate stemness, and CCR7 to promote tumorigenesis through a number of pathways, to the best of our knowledge this is the first study linking Notch1 to CCR7-dependent regulation of stem-like cells in mammary cancer." (PMID 28137279, 2017). "Moreover, CCR7 was shown to promote mammary cell tumorigenesis through amplification of stem-like cells which points to the key role played by the CCL21/CCR7 axis in the various steps of mammary tumor evolution." (PMID 28416768, 2017). "Moreover, blocking Notch activity prevented specific ligand-induced signaling of CCR7 and augmentation of mammary cancer stem-like cell function." (PMID 28137279, 2017). "In addition COX-2 expression by breast cancer cells can upregulate the expression of the chemokine receptor CCR7 via activation of EP2/EP4 receptors." (PMID 28056899, 2017). "Taken all together, our findings implicated the involvement of CCR7 in EMT, migration, and invasion of breast cancer cells, which may be through AKT signaling pathway." (PMID 28378417, 2017). "Crosstalk between CCR7 and Notch1 promotes stemness in mammary cancer cells and may ultimately potentiate mammary tumor progression." (PMID 28137279, 2017). "Using the MMTV-PyMT mouse model, we show here that CCR7 and Notch1 cooperate and crosstalk within transformed mammary stem cell-like compartments, indicating that the CCR7-Notch axis may be a potential target for therapeutic intervention in breast cancer." (PMID 28137279, 2017). "Since the chemotaxis of mDCs is mainly regulated via CCR7-CCL19 interaction, we examined whether breast cancer derived soluble factors increase the expression levels of CCR7 on mDCs." (PMID 27451948, 2016). "On the basis of the documented expression of CCR7 in breast cancer cells and its established role in mediating homing of DCs to lymph nodes, we speculated that CCR7 could have a role in guiding EMT cells toward lymphatic vessels." (PMID 25961925, 2016). "In addition, we provide clear evidence that expression of activated TAK1 is strongly associated with the up-regulation of CCR7 in tumor tissues confirming our previous results that TAK1 activation increases CCR7 expression in cultured breast cancer cells." (PMID 25557171, 2015). "Indeed, our results show that inhibition of CCR7 gene translates into significant decreases of VEGF-C expression in the analyzed breast cancer cells." (PMID 25744065, 2015). "Furthermore, higher CCR7 expression is correlated with compromised survival in breast cancer patients." (PMID 26313265, 2015). "Finally, we showed that protein kinase B (AKT) signaling pathway is the intracellular mechanism of CCR7-mediated VEGF-C secretion by human breast cancer cells." (PMID 25744065, 2015). "In addition, we have identified positive correlations between the CCR7 expression and lymphatic endothelial markers in the analyzed panel of breast cancer tissues." (PMID 25744065, 2015).
breast cancer (continued). "Furthermore, CCL21/CCR7 was also found to promote cancer cell migration into microlymphatic vessels in breast cancer, pancreatic tumor, lung adenocarcinoma, and esophageal squamous cell carcinoma." (PMID 25798926, 2015). "In addition, inhibition of aberrant sialylation of CCR7 suppresses proliferation and invasion and triggers anoikis in breast cancer cells." (PMID 24915301, 2014). "Unpublished results from our group indicate that the activation of CCR7 in the breast cancer cell line MCF7 leads to the activation of the oncoprotein cortactin and the promotion of cellular structures essential for metastasis like lamellipodia and invadopodia." (PMID 24305507, 2013). "In addition, higher CCR7 expression is correlated with lower survival and worse prognosis in breast cancer patients." (PMID 24259307, 2013). "CCR7 mRNA was highly expressed in most breast cancer cell lines and tissues from cancer patients." (PMID 22251626, 2012). "In addition, a reverse correlation in the expression of CCR7 and let-7a in breast cancer cell lines and breast cancer patient tissues was detected." (PMID 22251626, 2012). "Collectively, the results from the present study demonstrate let-7a suppresses metastasis through CCR7 target regulation and may be potentially useful as an antimetastatic agent in breast cancer." (PMID 22251626, 2012). "In the present study, among the metastasis-related genes as potential targets of let-7a, a reverse correlation between CCR7 and let-7a expression was observed in breast cancer patient tissues and breast cancer cell lines, and let-7a specifically influenced CCR7 downexpression." (PMID 22251626, 2012). "Notably, a reverse correlation between levels of let-7a and CCR7 expression was found in both human breast cancer patient tissues and in cancer cell lines." (PMID 22251626, 2012). "Overexpression of chemokines - especially of CXCR4 and CCR7 - was observed in breast cancer cells and surgical specimens, but chemokine receptors are also highly expressed in other tumour types including cancers of epithelial, mesenchymal and hematopoietic origin." (PMID 22253872, 2012). "Among the target proteins, CCR7 showed a significant reverse correlation with let-7a expression, suggesting that CCR7 could be regulated by let-7a in breast cancer cells." (PMID 22251626, 2012). "Similarly, breast cancer cells showing lymph node metastasis also show enhanced CCR7 expression, and breast cancer cell xenografts showed lymph node metastasis when CCR7 was expressed." (PMID 22505936, 2012). "Therefore, we suggest that let-7a reduces breast cancer cell migration and invasion through the downregulation of CCR7 expression." (PMID 22251626, 2012). "Moreover, as staining for CXCL12 and CCL21 (or CXCR4 and CCR7) was tightly linked in the group of primary tumors and lymph node metastasis tumors in this study, it is likely that a shared mechanism may account for variations in expression levels of both molecules in breast cancer." (PMID 20181250, 2010). "A study where breast cancer and melanoma cells were seeded into a collagen-Matrigel matrix and placed within a flow chamber has demonstrated that physiological levels of interstitial flow strongly induce their migration through autocrine C-C motif chemokine receptor 7 (CCR7) signaling." (PMID 37490147, 2023). "Although CCR7 is the primary chemokine receptor associated with lymph node metastasis, CXCR3, which may bind with moderate affinity to CCL21 in mice, has also been linked to lymph node chemotaxis in breast cancer and melanoma in a murine model." (PMID 35203305, 2022). "However, a possible physical association between CXCR4 and CCR7 or its functional significance in relation to breast cancer progression has not been previously investigated." (PMID 34685420, 2021).
breast cancer (continued). "However, the induced expression of CCR7 in breast cancer cells switches metastasis from the lung to lymph nodes, indicating that the organ specificities of metastatic cancer cells might be sufficient by a single chemical receptor." (PMID 32340161, 2020). "So, CCR7 may be the key factors that elevate the EMT process in breast cancer." (PMID 28378417, 2017). "Our results suggested that CCR7 may regard as a therapeutic target for the breast cancer treatment." (PMID 28378417, 2017). "Nevertheless, whether CCR7 is involved in the EMT progress of human breast cancer is unknown." (PMID 28378417, 2017). "We previously demonstrated that the chemokine receptor CCR7 promotes mammary tumorigenesis via amplification of stem-like cells, and we now show here that crosstalk between Notch and CCR7 signaling promotes breast cancer stemness and may be a potential target for these new therapies." (PMID 28137279, 2017). "Furthermore, CCR7 was accompanied with EMT in human breast carcinoma 16 and gastric cancer." (PMID 28378417, 2017). "Finally, we investigated whether the expression of CCR7 and CCL21 could be linked to EMT in human breast cancer." (PMID 25961925, 2016). "In addition, the expression of CCR7 has been reported to promote cancer cell metastasis to lymph nodes in nonsmall cell lung cancer, breast cancer, squamous cell carcinoma of head and neck cancer, colorectal cancer, prostate cancer, esophageal squamous cell cancer and gastric cancer." (PMID 25798926, 2015). "Therefore, inhibition of metastasis can be a major goal, and we noted that C-C chemokine receptor type 7 (CCR7) is a reasonable therapeutic target in breast cancer therapy, because expression of CCR7 is reportedly correlated with lymphatic metastasis and poor prognosis in breast cancers." (PMID 22251626, 2012). "Therefore, we studied the inhibition of CCR7 expression in breast cancer cells." (PMID 22251626, 2012). "Cell motility was more asymmetric at CCL19 concentrations close to the CCR7 dynamic kinetic binding constant, suggesting that CCL19 is involved in regulating tumor cell heterogeneity and invasive ability in the breast cancer microenvironment." (PMID 37864213, 2023). "The study of CCR7/CCL19 chemokine axis and breast cancer (BC) prognosis and metastasis is a current hot topic." (PMID 37864213, 2023). "In vitro, endothelin activation of ETA correlated with increased CCR7 cell surface expression in MCF-7, SKBR3 and MDA-MB-231 human breast cancer cell lines, which enhanced MCF-7 invasion of Matrigel towards CCL21 or CCL19 only in the presence of endothelin." (PMID 35203305, 2022). "The expression of COX-2, CCR7, and the prostaglandin E2 receptors (EP2 and EP4) correlated with lymph node metastasis of breast cancer." (PMID 35203305, 2022). "CCR7, CCL21 and miR-let-7a were detected in both breast cancer cell lines and patient breast cancer tissue." (PMID 35203305, 2022). "In these studies, ectopic expression of COX-2 in MCF-7 breast cancer cells resulted in upregulation of CCR7 on the cell surface, while knockdown of COX-2 by small hairpin RNA led to reduced CCR7 expression." (PMID 35203305, 2022). "Targeting a single paracrine signaling pathway, e.g., CCL21/CCR7 or CXCL12/CXCR4, has been shown to reduce lymphatic metastasis in murine models of breast cancer." (PMID 34885152, 2021). "Together with our earlier observations in primary mammary tumour cells, these results suggest that functional CXCR4 and CCR7 heterodimers are present at the later invasive stage of cancer progression." (PMID 34685420, 2021). "CCR7 chemokine receptor binds to the ligand CCL19/CCL21 and promotes lymphogenesis and metastasis in breast cancer." (PMID 34544443, 2021). "In breast cancer cells, let-7a directly binds to the 3′UTR of the C-C chemokine receptor type 7 (CCR7) to suppress its expression, leading to impaired migration and invasion." (PMID 34572067, 2021).